CD4 (CD4 molecule)
Diseases named in the same sentence as CD4 in open-access papers (continued):
Sharing a sentence is not in itself a finding about the gene and the disease.
mastitis (36 papers, 2012 to 2025). Inflammation of breast tissue during lactation or postpartum due to an obstructed duct or infection. "Similar trends for all the genotypes in SNPs (TRAPPC9 and CD4) that were found for their association with serum cytokines and mastitis resistance phenotypic traits were also reported in expression analysis." (PMID 36213405, 2022). "In general, the present study using a newly designed CCSC-I for genotyping to validate the association of SNPs in TRAPPC9 and CD4 genes with milk production and mastitis resistance traits." (PMID 36213405, 2022). "Our results also confirm earlier findings that CD4 count, plasma viral load, and subclinical mastitis are independently associated with HIV shedding in breast milk." (PMID 31689745, 2019). "Further evidence for a role of CD4+ in protection against mastitis is provided by the recent identification of a single-nucleotide polymorphism in the bovine CD4 gene, which is associated with SCC." (PMID 23776543, 2013). "Furthermore, the DNA methylation alterations in some immune-related genes, such as CXCR1, IL6R, TLR4, NCKAP5, CSN1S1, and CD4, have been found to participate in the regulation of gene expression during mastitis caused by E.coli or S. aureus." (PMID 38486242, 2024). "In addition, abnormal DNA methylation at the CpG site in the 1 kb promoter region of JAK2, STAT5A and CD4 genes caused by mastitis can be used as a potential epigenetic marker to estimate mastitis susceptibility in dairy cows." (PMID 37569258, 2023). "In the present study, the polymorphisms in TRAPPC9 and CD4 genes that cause variation in the economic and health traits (milk production and mastitis resistance phenotypic traits) were selected from our previous studies and analyzed for validation in a new and larger population by using CCSC-I." (PMID 36213405, 2022). "Findings of the current study inferred that aberrant DNA methylation in the CpG sites at the 1 kb promoter region in JAK2, STAT5A, and CD4 genes due to mastitis in cows can be used as potential epigenetic markers to estimate bovine mastitis susceptibility in dairy cattle." (PMID 35011171, 2021). "A previous study reported that mastitis caused the increasing of CD4+ cells in the milk of cattle." (PMID 30823555, 2019). "Therefore, the observed decrease in the proportion of CD4+CD8+ T cells within mammary gland tissues affected by subclinical mastitis in this study may suggest an elevated risk of mastitis infection in dairy cows." (PMID 41142813, 2025). "In bovine mastitis research, CD4+CD8+ DP T cells have been shown to participate in various immune functions, influencing cytokine production and thereby modulating immune responses." (PMID 41573562, 2025). "In our investigation into the role of T cells in the anti-inflammatory effects of ammonia on mastitis, we observed that, compared to the control group, the activity of CD4-positive T cells was significantly diminished in the ammonia-treated group." (PMID 40370468, 2025). "The findings indicate that the proportion of CD4+CD8+ double-positive (DP) T cells in milk is significantly reduced in cows with subclinical mastitis compared to healthy cows." (PMID 41142813, 2025). "The expression of this gene was negatively correlated with high methylation of CD4 in the mastitis group." (PMID 39045327, 2024). "Infection of the mammary gland during lactation leads to clinical mastitis, which causes a rise in SCC in milk and CD4+ T lymphocytes." (PMID 39045327, 2024). "RT-qRCR analysis showed that the mastitis group had significantly reduced expression of CD4 and TRAPPC9 genes compared to the control group (p < 0.05)." (PMID 39045327, 2024). "It was found that the expression of TRAPPC9 and CD4 genes was reduced in cows with mastitis, with the expression of TRAPPC9 induced by inflammation showing the same trend." (PMID 39045327, 2024).
mastitis (continued). "The CpG islands in the promoter regions of JAK2 and STAT5A gene were found to be hypomethylated, resulting in increased gene expression in cows with mastitis compared to healthy controls; the opposite was seen with the CD4 gene." (PMID 39045327, 2024). "For instance, hyper-methylation of the promoter region of CD4 gene was found to negatively correlate with its gene expression changes during mastitis." (PMID 38486242, 2024). "Polymorphisms in CD4 and STAT5B genes and their link with mastitis resistance phenotypic traits have been well studied." (PMID 36911690, 2023). "During mastitis, the inflammatory cells are recruited to the site of infection, where T cells, particularly CD4 cells, were predominantly observed." (PMID 36911690, 2023). "Dairy cattle fed probiotic bacteria at the onset of mastitis had decreased days on medication and increased CD4+ and CD11c, Cd172high dendritic cells." (PMID 38004631, 2023). "The polymorphism in CD4 at loci g.13598C>T has been identified for its significant association with SCS, which is a crucial indicator of mastitis." (PMID 36911690, 2023). "Genetic effect of SNPs in TRAPPC9 and CD4 genes on milk production, mastitis resistance and serum cytokine traits in Chinese Holstein." (PMID 36213405, 2022). "The associations of polymorphisms in CD4 and TRAPPC9 genes with milk production and mastitis resistance traits have been documented in previous reports." (PMID 36213405, 2022). "We recommend carrying out further research to verify the functional role of DNA methylation in promoter CpG islands of the CD4 gene in mastitis resistance studies." (PMID 35011171, 2021). "The evaluation of DNA methylation in promoter regions of JAK2 and STAT5A revealed hypo-methylation levels of CpG sites and higher gene expression in cows diagnosed with mastitis as compared to the healthy control, and vice versa in those with CD4." (PMID 35011171, 2021). "The CpG islands in the promoter regions of the JAK2 and the STAT5A revealed hypo-methylation levels and higher gene expression in cows with mastitis compared to the healthy control, and vice versa in those with the CD4 gene." (PMID 35011171, 2021). "In the previous study, it was noticed that polymorphisms in CD4 and STAT5B genes are significantly linked with mastitis-resistance phenotypic traits." (PMID 33202860, 2020). "Major factors driving this shedding were low CD4 count, unsuppressed plasma viral load and severe sub-clinical mastitis." (PMID 31689745, 2019). "Our previous research revealed that bovine mastitis enhances the level of methylation in the promoter of CD4 molecule (CD4) and alternatively decreases the expression of CD4 by blocking the transcription factor binding." (PMID 31010979, 2019). "In mastitis, CD4+ T cells are mainly activated with recognition of complex molecules, which form between histocompatibility complex (MHC) II molecules or by antigen-presenting cells (APCs), B cells, and macrophages." (PMID 30823555, 2019). "Taking the up-regulated CD4 gene as an example, which has an important function in the development of immunity, was down-regulated in mastitis cows." (PMID 31010964, 2019). "Cows having substantially more CD4+ T cells than CD8+ T cells in their mammary gland secretions appear to be more mastitis-resistant suggesting that CD4+ T cells are protective." (PMID 26999219, 2016). "Pathogenesis of HIV-1 transmission through breastfeeding is not completely understood but certain risk factors, including low maternal CD4 count, high plasma or breast milk HIV-1 RNA and mastitis have been associated with increased transmission." (PMID 25812161, 2015). "Risk factors for breast milk transmission of HIV-1 from mother to child include high plasma and breast milk viral load, low maternal CD4 count and breast pathology such as mastitis." (PMID 25812161, 2015).
mastitis (continued). "In this study, adaptive immunity, particularly the CD4+ cell-mediated adaptive immune responses, was investigated at the cellular and molecular levels in the murine S. aureus mastitis model." (PMID 26230498, 2015). "Additional maternal factors include seroconversion during lactation, CD4+ T cells counts below 500 cells per mm3, poor breast health (mastitis, nipple bleeding, etc), and decreased levels of alpha-defensins in breast milk." (PMID 22737068, 2012). "Based on the published studies, it can be concluded that CD4 might be a valuable addition to the genetic markers for mastitis resistance in dairy cattle." (PMID 36911690, 2023). "Keeping in view the importance of the SNP Chip from various published studies we used this technique in the present study to validate the role of the significant variants from our previous studies in CD4 and TRAPPC9 genes for production and mastitis resistance traits." (PMID 36213405, 2022). "The results verify that the documented SNPs in both genes (TRAPPC9 and CD4) could be considered as powerful genetic markers against bovine mastitis resistance." (PMID 36213405, 2022). "The present study was designed to evaluate the association of polymorphisms in bovine trafficking protein particle complex subunit 9 (TRAPPC9) and cluster of differentiation 4 (CD4) genes with milk production and mastitis resistance phenotypic traits in a different cattle population." (PMID 36213405, 2022). "During bovine mastitis, CD4+ T lymphocytes, activated upon antigen recognition, dominate." (PMID 35335696, 2022). "Altogether, our findings suggested that the SNPs of TRAPPC9 and CD4 genes could be useful genetic markers in selection for milk protein improvement and mastitis resistance phenotypic traits in dairy cattle." (PMID 36213405, 2022). "Furthermore, cows having higher frequency of T CD4+ lymphocytes than T CD8+ lymphocytes in their mammary gland secretions appear to be more resistant to mastitis." (PMID 34433467, 2021). "Hence, these results are promising, suggesting that DNA methylation at the promoter region of CD4 can be considered as a potential epigenetic marker for mastitis resistance." (PMID 35011171, 2021). "Furthermore, the polymorphism in CD4 at locus g.13598C>T showed a significant association with SCS, which is the crucial indicator of mastitis." (PMID 33202860, 2020). "The RT-qPCR results showed that both the TRAPPC9 and CD4 genes were expressed in the blood of cattle in the healthy and mastitis groups, and the expression levels of both genes were significantly higher in cows from the control group than those from the mastitis group (p < 0.05)." (PMID 39045327, 2024). "As expected, the result of flow cytometry showed that E. coli injection led to a remarkable reduction of CD4+ T cell counts compared with the control group, and Z. morio hemolymph or gentamicin administration significantly reversed this reduction in E. coli-induced mice mastitis." (PMID 36362066, 2022). "For this purpose, these SNPs in TRAPPC9 and CD4 genes were detected by a new technique, i.e., Chinese Cow's SNPs Chip-I (CCSC-I) and genotyped in a different and a bit larger Chinese Holsteins population to explore their association with mastitis resistance and milk production phenotypic traits." (PMID 36213405, 2022). "In this study, the relatively lower concentration of CD4 and CD8 in the serum of animals with HSCC indicated their dysfunction in such dairy cows, which further lowered the ability of lymphocytes to resist diseases and increased the risk of postpartum mastitis in dairy cows." (PMID 32408873, 2020). "However, there are also contrasting reports of lowered CD4+:CD8+ ratios in S. aureus mastitis." (PMID 26999219, 2016). "Collectively, these findings indicate that ammonia treatment significantly diminishes the viability and proliferation of both CD4+ and CD8+ T cells in LPS-induced mastitis, thereby contributing to the observed anti-inflammatory effects." (PMID 40370468, 2025).
mastitis (continued). "The CD4+, CD8+ T cells of cows with mastitis expressed significantly higher single-cytokine (TNF-α or IL-2) than those of healthy cows." (PMID 36960295, 2023). "Our results, for the first time, revealed a potential role of IgG+CD27+ B cells, CD4+CD8+ T cells and WC1+ γδ T cells in the defense of B. contaminans-induced mastitis in cows." (PMID 36960295, 2023). "Three SNPs in TRAPPC9 and one SNP from CD4 gene were screened through CCSC-I and genotyped in a total of 312 (156: Mastitis, 156: Healthy) Chinese Holstein population." (PMID 36213405, 2022). "The increase of αβ T cells in the milk was mainly due to CD4+ T cells, and several groups reported increased CD4+:CD8+ ratios in cattle with mastitis." (PMID 26999219, 2016). "Moreover, in cows diagnosed with mastitis, the methylation of the STAT5A promoter was lowest compared with JAK2 and CD4, about 9–11%, but the expression of STAT5A still changed significantly." (PMID 40214477, 2025). "Through flow cytometric analysis of milk, nonspecific mastitis revealed the highest percentage of CD4+ T lymphocytes, the percentage of CD8+ T lymphocytes was found to be highest in infectious bacterial mastitis." (PMID 39399489, 2024). "Therefore, we used FCM to analyze the changes of CD4, CD8, and γδ T cells of cows with B. contaminans naturally-induced mastitis." (PMID 36960295, 2023). "At the individual animal level, the most significant correlation between immune and health traits was the negative association between CD4+:CD8+ ratio and SCC, a useful indicator of intra-mammary infection and mastitis." (PMID 23776543, 2013). "In addition, the increase in milk CD4+ T cells was documented to be correlated with non-specific mastitis which suggested their link with low bacterial shedding." (PMID 36213405, 2022). "A number of significant correlations were found between immune traits and other recorded traits including: CD4+:CD8+ T lymphocyte ratio and subclinical mastitis; % CD8+ lymphocytes and fertility; % CD335+ natural killer cells and lameness episodes; and serum haptoglobin levels and clinical mastitis." (PMID 23776543, 2013). "Consequently, H3K27me3 levels in healthy cows were higher than in S. aureus mastitis cows for both genes (CD4 and IL10), which means that increased H3K27me3 level repressed pro-inflammatory gene expression (IL10) in healthy dairy cattle and vice versa in S. aureus mastitis cows." (PMID 27503467, 2016). "After adjustment for maternal age, HAART use, and CD4 count and infant birth weight and gestational age, the difference in milk CMV DNA load by subclinical mastitis remained nonsignificant." (PMID 24723745, 2014).
nasopharyngeal carcinoma (36 papers, 2007 to 2025). A carcinoma arising from the nasopharyngeal epithelium. "AURKA showed a negative correlation with the infiltration of B cells, CD8+ T cells, and T cell regulatory cells, but a positive correlation with CD4+ T cell Th2 in nasopharyngeal carcinoma." (PMID 39585848, 2024). "Here, to evaluate the therapeutic potential of CD4 TCR-T in nasopharyngeal cancer, we screened for CD4 TCRs recognizing EBV nuclear antigen 1 (EBNA1) presented by HLA-DP5." (PMID 38412034, 2024). "Nasopharyngeal carcinoma-derived vesicular galectin-9 induced apoptosis in CD4+ T cells via interaction with Tim-3, as well as impairing T-cell function by interaction with TIM3 receptor on DCs in glioblastoma." (PMID 36612080, 2022). "The finding that LMP-1, an oncoprotein of Epstein-Barr virus, upregulates M-Sec in nasopharyngeal carcinoma cells through NF-κB activation also supports M-Sec induction in CD4+ T cells by the Tax-NF-κB cascade." (PMID 34843591, 2021). "The proportion of M1 macrophages was higher in nasopharyngeal carcinoma, while memory B cells and resting memory CD4+ T cells were relatively lower." (PMID 33816234, 2021). "Our study shows that the composition of tumor T cells changes significantly during the recurrence of nasopharyngeal carcinoma, both in the number of CD4+ cells and in the CD4+/CD8+ ratio." (PMID 34422839, 2021). "Then this result, the local tumor microenvironment of recurrent nasopharyngeal carcinoma after radiotherapy is altered in the case of certain chemokines and cytokines that contribute to the accumulation of CD4 expression positive cells toward the tumor." (PMID 34422839, 2021). "In nasopharyngeal carcinoma, patients with higher CD4+/CD8+ T-cell ratios showed a better survival than patients with lower ratios." (PMID 32082401, 2020). "Exosomal packaging, which has been shown to induce apoptosis of EBV-specific CD4+ cells in nasopharyngeal carcinomas, can describe a route for intracellular Gal-9 to become an extracellular effector." (PMID 24859692, 2014). "The frequency and suppressor functions of CD4+CD25highCD127lowFoxP3+regulatory T cells (Treg) are also higher in nasopharyngeal carcinoma patients (NPC) than healthy donors." (PMID 26082068, 2012). "Additionally, we found that 62% of nasopharyngeal cancer patients showed 50%–100% expression of HLA-DP on tumor cells, indicating that nasopharyngeal cancer is well suited for CD4 TCR-T therapy." (PMID 38412034, 2024). "However, in EBV‐associated nasopharyngeal carcinoma (NPC), the presence of PD‐1+ CXCR5− CD4+ Th‐CXCL13 cells within TLS may be associated with improved prognosis." (PMID 40591148, 2025). "TDEs from nasopharyngeal carcinoma (NPC) have also been found to contain galectin-9, a ligand for Tim-3, which induces apoptosis in mature Th1 and CD4+ T cells, further dampening T cell function." (PMID 40693234, 2025). "Signaling between CD70 and CD27 was identified as the only significant contact interaction between CD4+ naïve T cells, Tregs, and nasopharyngeal carcinoma (NPC) cells in the TME." (PMID 37828948, 2023). "However, study also indicated that wild-type oncolytic viruses may be effective against nasopharyngeal carcinoma by directly activating the helper CD4+ T cell response, possibly because different virus types have different changes in peripheral blood T lymphocyte subsets." (PMID 40661951, 2025). "A novel subpopulation of tumor-derived PD-1 + CXCR5_ CD4 + Th-CXCL13 cells has been discovered through research and plays a significant role in driving B cells into TLSs in nasopharyngeal carcinoma." (PMID 38216927, 2024). "A CD4+ T cell receptor specific to HLA-DP5-restricted EBNA1567-581, provides a strategy for Epstein-Barr virus-related nasopharyngeal cancer immunotherapy in HLA-DP5+ patients." (PMID 38412034, 2024). "Those samples with microscopically confirmed nasopharyngeal cancer were tested for EBNA1, LMP1, CD4, CD8, and FOXP3 concentration with ELISA, then verified with IHC." (PMID 35963999, 2022).